ENSG00000207503
Synonyms: LOC124900472
Gene: Small nucleolar RNA gene on chromosome 21 (41,539,206 to 41,539,326, forward strand). Ensembl gene ENSG00000207503.
Gene Ontology:
Biological process: RNA processing
Cellular component: nucleolus
Homologues: Orthologues: rat LOC120095737 (72% identical), rat Snora32 (67% identical), rat LOC120097588 (64% identical), rat LOC120102640 (49% identical), rat LOC120100386 (41% identical), rat LOC120098685 (40% identical). Paralogues in human: SNORA32 (82% identical).